CXCL2 (C-X-C motif chemokine ligand 2)
Diseases named in the same sentence as CXCL2 in open-access papers (continued):
Sharing a sentence is not in itself a finding about the gene and the disease.
hyperreactivity (2 papers, 2019 to 2022). "We measured BAL CCL11 (eotaxin, an eosinophil chemoattractant), IL-23p19, IL-6, CXCL2 (pro-neutrophilic mediators), CCL20 (a lymphocyte chemoattractant), and IL-13 (known to prime smooth muscle cells for airway hyperreactivity)." (PMID 31572383, 2019). "Similar experiments demonstrated that neutralization of CXCR2, the receptor for the chemokines CXCL1, CXCL2, granulocyte chemoattract protein 2, and LPS-induced CXC chemokine, prevents RSV-induced airway hyperreactivity but does not alter viral clearance." (PMID 35062301, 2022).
keratitis (2 papers, 2009 to 2017). A corneal disease that is characterized by inflammation of the cornea. "CXCL2 gene had the highest fold change in BK among the chemokines and this gene promotes persistent neutrophil influx even in later stages of keratitis." (PMID 28573109, 2017). "Because neutrophils appeared by histology and flow cytometry to be the predominant infiltrating cell in HAdV-D53 keratitis, we also tested the expression of neutrophil chemokines CXCL1 and CXCL2." (PMID 19492050, 2009).
kidney damage (2 papers, 2022 to 2023). "Meanwhile, in the pathological state of kidney damage, there are proinflammatory tubular cells that are characterized by increased expression of CXCL2, which may be closely related to ESRD." (PMID 37287620, 2023).
Klebsiella pneumonia (2 papers, 2014 to 2015). An pneumonia caused by infection with Klebsiella. "Jeyaseelan and colleagues reported that CXCL1 regulates expression of CXCL2 and CXCL5 during murine Klebsiella pneumoniae pneumonia." (PMID 25621893, 2015).
Lewis lung carcinoma (2 papers, 2019 to 2021). "For example, in Lewis lung carcinoma in addition to IL-1 receptor induction of proangiogenic chemokine CXCL2 driving tumor promoting angiogenesis, IL-1β driven neovascularization was found to be dependent on infiltrating cyclooxgenase 2 (COX-2) positive macrophages." (PMID 31293586, 2019). "While in Lewis lung carcinoma, IL-1β drives tumor growth through its upregulation of VEGF and the proangiogenic chemokine (C-X-C motif) ligand 2 (CXCL2)." (PMID 31293586, 2019).
metastatic cancer (2 papers, 2021 to 2025). A carcinoma which has spread from the original site of growth to another anatomic site. "Intriguingly, APM‐treated tumor cells in mice exhibited downregulated expression of the chemokine CXCL2, known to contribute to bone osteolysis in metastatic cancer, and downregulation of the CXCL2 production pathway." (PMID 40433925, 2025). "Interestingly, several well-known oncogenes linked to aggressive and metastatic cancer phenotype, including CXCL1, CXCL2, MYC, and BMP4, were included in this gene get, suggesting that BRD4 and STAT3 can coordinately regulate the oncogenic enhancer activity to promote tumor progression." (PMID 34290255, 2021).
metastatic prostate carcinoma (2 papers, 2019 to 2022). A carcinoma that arises from the prostate gland and has spread to other anatomic sites. "A recent study also reports the contribution of CXCR2 ligands CXCL1 and CXCL2 to osteolysis in metastatic prostate cancer." (PMID 30871004, 2019).
mucositis (2 papers, 2018 to 2019). Mucositis is inflammation and damage of the mucous membranes lining the mouth and other parts of the gastrointestinal (GI) tract. "A transcription quantitative real-time PCR (RT-qPCR) analysis demonstrated that cultured MSCs at passage six expressed very low levels of chemokine receptors, including CXCR2, which is the receptor of the chemokine that is highly expressed in mucositis, CXCL2." (PMID 29445104, 2018). "Increased oral neutrophils during mucositis may be the result of upregulation in chemoattractants such as CXCL2 by the epithelium, as seen in our transcriptome data, in combination with barrier defects through which neutrophils escape tissues." (PMID 31018870, 2019).
myocarditis (2 papers, 2023 to 2025). Myocarditis is a condition that is characterized by inflammation of the heart muscle (myocardium). "Nuclear factor kappa-light-chain-enhancer ofactivated B (NF-κB) is a key inflammation-related transcription factor.In myocarditis, the activation of NF-κB is closely related to theupregulation of chemokines, including CCL2, CCL3, and CXCL2." (PMID 40927089, 2025). "In a murine CoxsackievirusB3 (CVB3)-mediated myocarditis model, during infection, CVB3 upregulates theexpression of chemokines (CXCL1, CXCL2, and CXCL3) in the heart, continuouslyattracting neutrophils from the peripheral blood." (PMID 40927089, 2025).
neuropathy (2 papers, 2019 to 2022). A disorder affecting the nervous system that manifests with pain, tingling, numbness, and/or muscle weakness. "However, the spinal protein level of CXCL2 did not change after injury, suggesting that under neuropathy, CXCL2 plays an important role in the PNS (peripheral nervous system) rather than the CNS." (PMID 31616413, 2019).
oral cancer (2 papers, 2015 to 2020). "CXCL2 and CXCL13 are associated with bone destruction in oral cancer and promote tumor invasion." (PMID 33330624, 2020). "Several chemokine ligands (chemokine (C-C motif) ligand 3 (CCL3), chemokine (C-X-C motif) ligand 2 (CXCL2), and chemokine (C-X-C motif) ligand 3 (CXCL3)) also demonstrated >25-fold overexpression in 4-NQO-induced oral cancers." (PMID 25635769, 2015). "The chemokine ligands, CCL3, CXCL2, and CXCL3, were each overexpressed by > 25-fold in NQO-induced oral cancers." (PMID 25635769, 2015).
ovarian adenocarcinoma (2 papers, 2021). An adenocarcinoma that arises from the ovary. "The previous study has also suggested that CXCL2 concentration was up-regulated in the serum of ovarian adenocarcinoma patients with chemoresistance." (PMID 34474677, 2021).
Peri-Implantitis (2 papers, 2019 to 2022). An inflammatory process with loss of supporting bone in the tissues surrounding functioning DENTAL IMPLANTS. "Our study was the first clinical investigation to find a higher level of CXCL2 in PICF of peri-implantitis." (PMID 36233685, 2022). "Neutrophil recruitment is regulated by pro-inflammatory cytokines, such as CXCL2; we found that this molecule was expressed in the peri-implant (or peri-implantitis affected) tissues." (PMID 31242601, 2019). "As expected, the presence of inflammatory cytokines and chemokines, particularly IL1B, IL6, its signal transducer IL6ST, and CXCL2, was clearly observed at the mRNA level in the peri-implantitis affected samples." (PMID 31242601, 2019). "Additionally, these clinical indexes were also associated with cytokine levels in peri-implantitis in this study, which showed that IL-1β, IL-6, IL-17A, VEGF, CXCL2, and G-CSF had a positive correlation with these three clinical indexes." (PMID 36233685, 2022). "Further study is required to investigate the function of CXCL2 in peri-implantitis." (PMID 36233685, 2022). "Significant higher levels of chemokine CXCL2 (331.7 (214.1, 672.8) pg/mL vs. 1220.5 (726.3, 1880.0) pg/mL; p < 0.001; q = 0.002) were found in the PICF of peri-implantitis implants compared to healthy implants, with a fold change of 3.4." (PMID 36233685, 2022). "In this study, chemokines of CXCL2, IL-8, MCP-1, Eotaxin, and RANTES were significantly higher in peri-implantitis than those in healthy implant sites." (PMID 36233685, 2022).
pneumonitis (2 papers, 2016 to 2025). An inflammatory process affecting the lung parenchyma. "They reported normal neutrophil migration toward the cytokine macrophage inflammatory protein-2 (MIP-2, also known as CXCL2) or the anaphylatoxin C5a in vitro, and normal neutrophil infiltration into lungs in a model of immune complex-induced pneumonitis." (PMID 26764049, 2016). "Previous studies have reported that fibrogenic cytokines including CXCL1, CXCL2, TNF-α, and CXCL8 are involved in bleomycin-induced pneumonitis." (PMID 41425704, 2025).
polyp (2 papers, 2024). A usually exophytic mass attached to the underlying tissue by a broad base or a thin stalk. "Baseline probability associated with polyp’s size was affected solely by CXCL2." (PMID 38338661, 2024). "There was also a clear elevation in CXCL2 expression in normal and polyp tissue as well as in P/N value for polyps with adenocarcinomas, which, however, lacked statistical significance due to low sample number." (PMID 38338661, 2024). "In turn, polyp size significantly affected CXCL2 expression in normal mucosa, which displayed an upward trend along with increasing polyp size and a significant difference between medium and large polyps." (PMID 38338661, 2024). "Its increasing expression in adjacent tissue would decrease the likelihood of malignant transformation resulting from the size of neoplasm, further supporting the conclusion on positive role played by CXCL2 in polyp’s microenvironment." (PMID 38338661, 2024). "An increase in CXCL2 expression in normal mucosa is likely to diminish the probability of malignancy associated with polyp size, as indicated by the relatively high, negative value of φ." (PMID 38338661, 2024). "In patients stratified based on polyp type, CCL4 expression differed significantly between lesion and normal mucosa in V while CXCL2 expression differed between lesion and normal mucosa in T and T-V." (PMID 38338661, 2024). "Regarding CXCL2, which did not display any significant relation to polyp characteristics if determined in lesions, we found its expression in non-transformed mucosa to correlate with three out of four polyp-associated risk factors, that is, histological type and size and dysplasia grade." (PMID 38338661, 2024).
pulmonary TB (2 papers, 2020 to 2023). "Similarly, an earlier study has shown that treatment with a PDE4i such as roflumilast and rolipram controlled the neutrophil recruitment by reducing TNF-α, IL-6, CXCL1, and CXCL2/3 in a rabbit model of pulmonary TB." (PMID 37854602, 2023).
pyelonephritis (2 papers, 2012 to 2019). An inflammatory process affecting the kidney. "Flagellin also activates renal collecting duct cells via TLR5, which enables upregulation of CXCL1 and CXCL2 to provide renal host defense against pyelonephritis." (PMID 31776239, 2019).
respiratory infection (2 papers, 2017 to 2020). "Next, we wanted to understand how the microbiota drives this common innate response to respiratory infection and whether the effect of the microbiota on enhancing respiratory defenses was mediated by GM-CSF, CXCL1, or CXCL2." (PMID 29142211, 2017).
SARS-CoV infection (2 papers, 2013 to 2022). "As a result of miRNA-223 inhibition, mRNA expression levels of NLRP3 inflammasome and pro-inflammatory chemokines CXCL10, CXCL2, and IL-1ß were increased, suggesting a contribution of miR-223-3p in vivo to limit excessive lung inflammation induced by SARS-CoV infection." (PMID 35229638, 2022). "Similarly, DUSP8, IL6, CXCL10, and NFKBIA are up-regulated in SARS patients, while PTX3 and CXCL2 have been shown to be involved in SARS-CoV infection." (PMID 23935999, 2013).
skin infection (2 papers, 2020 to 2021). An inflammatory process affecting the skin, caused by bacteria, viruses, parasites, or fungi. "The local CXCL1 and CXCL2 synthesis decrease with age, thus promoting infection spread in a mouse model of soft-tissue and skin infection." (PMID 31936467, 2020).
type 2 diabetes (2 papers, 2022 to 2025). "The transcriptomic response, and in particular the production of exerkines responsive to hypoxia, such as CXCL2 and CXCL12, suggests that the exercise-induced inflammation signature in individuals with type 2 diabetes may arise from insufficient local oxygenation of working skeletal muscle." (PMID 36070371, 2022).
uveitis (2 papers, 2012 to 2021). An inflammatory process affecting a part of or the entire uvea. "In conclusion, our study showed that uveitis associated with TB featured increased aqueous levels of IL-6, CXCL2, CXCL8, CXCL9, and CXCL10, which is not typical of an active ocular TB infection." (PMID 22509092, 2012). "As for the genes in the non-lymphoid cells, both Cxcl2 (rescued in monocytes and neutrophils) and Cxcl10 (rescued only in monocytes) possibly contributed to the progression of uveitis by recruiting T cells and DCs." (PMID 34484247, 2021).
Vaginal infection (2 papers, 2019 to 2023). "Vaginal infection with C. albicans resulted in a strong inflammatory response, including elevated concentrations of proinflammatory cytokines IL-1β and CxCL-2 (a murine cytokine with similarities to human IL-8), as well as neutrophil infiltration." (PMID 38055800, 2023).
Acanthamoeba infection (1 paper, 2014). "Thus, outcomes of PMN infiltration in corneas strongly support increased level of CXCL2 in Chinese hamster corneas 3 and 7 days after Acanthamoeba infection." (PMID 24633052, 2014).
acute myeloid leukemia (1 paper, 2025). Acute myeloid leukemia (AML) is a group of neoplasms arising from precursor cells committed to the myeloid cell-line differentiation. "Finally, we also observed a decrease in the expression of CXCL2 that might play a key role in the escape of acute myeloid leukemia from treatment." (PMID 40028321, 2025).
alcohol (1 paper, 2019). "In addition, Stat3 in hepatocytes is involved in induction of CXCL2 and CCL2 expression followed by increased infiltration of inflammatory cells in an alcohol liver injury model." (PMID 31718093, 2019).
allergic contact dermatitis (1 paper, 2025). An inflammatory skin condition caused by an immune response to direct contact between the skin and an allergen. "Moreover, the pronounced suppression of CXCL2 and IL-1β by PjELNs in this study likely accounts for the reduction in neutrophil infiltration, which is a key driver of tissue damage and symptom severity in allergic contact dermatitis." (PMID 41296413, 2025).
Alzheimer disease (1 paper, 2024). A progressive, neurodegenerative disease characterized by loss of function and death of nerve cells in several areas of the brain leading to loss of cognitive function such as memory and language. "CXCL2 is elevated in Alzheimer’s disease and amyotrophic lateral sclerosis (ALS)." (PMID 38931342, 2024).
anthrax (1 paper, 2015). "Elevated transcription of TNF-α, IL-1α, IL-1β, IL-4, IL-6, CCL5, CXCL2 and KC have been observed in both murine anthrax challenge models and in vitro macrophages and monocytic cell lines exposed to anthrax antigens." (PMID 26075052, 2015).
aortic aneurysm (1 paper, 2025). A ruptured aneurysm located in the wall of the proximal portion of the descending aorta proceeding from the arch of the aorta. "C-X-C motif chemokine ligands (CXCLs) demonstrate high levels of intercellular communication signaling in aortic aneurysms, and blocking the binding of CXCL2 to receptor CXCR2 can significantly reduce the extent of aortic dilation." (PMID 40141310, 2025).
ascending aortic aneurysm (1 paper, 2025). "In accordance, either knockdown of Tnfα or Igf1 in CX3CR1+ macrophages reduced vascular inflammation, as evidenced by the downregulation of Mcp1, Il6, and Cxcl2, and subsequently ameliorated both aortic root and ascending aortic aneurysm progression as well as related aortic wall pathologies." (PMID 39817456, 2025).
Ataxia (1 paper, 2018). Ataxia refers to impaired coordination of voluntary muscle movement. "When IFNγ signaling is impaired, myeloid cell production of CXCL2 increases, which promotes brainstem inflammation and results in clinical ataxia." (PMID 30012158, 2018). "The ELR+ CXC chemokine, CXCL2, is elevated in the brainstem during aEAE and plays a critical role in the development of ataxia." (PMID 30012158, 2018).
bladder tumors (1 paper, 2022). "Comparison of chemoattractants expression during MB49 bladder tumors grow highlighted CCL8 and CCL12 (CCR2-ligands), CCL9 and CCL6 (CCR-1-ligands), CXCL2 and CXCL5 (CXCR2-ligands), CXCL12 (CXCR4-ligand) and antagonist of C5/C5a as potential targets to decrease myeloid suppressive cells." (PMID 36613562, 2022).
brain infarcts (1 paper, 2024). "Besides, CXCL2‐neutralizing antibody significantly reduced brain infarct." (PMID 39135337, 2024).
bronchiolitis (1 paper, 2022). Inflammation of the bronchioles characterized by swelling of the bronchioles and mucus accumulation. "Additionally, in mock-primed mice, the degree of neutrophilic infiltration and the increased expression of chemokines and neutrophil activators, especially CXCL1 and CXCL2, into the lungs following PVM inoculation has been positively correlated with the severity of hRSV-induced bronchiolitis." (PMID 35062301, 2022).
brucellosis (1 paper, 2024). Brucellosis is a bacterial infection that spreads from animals to people via unpasteurized dairy products or by exposure to contaminated animal products or infected animals. "We found that NK cells, especially for NK_Naive, NK_Memory and NK_CD56(dim), in brucellosis patients potentially underwent migration, with several migration‐related genes highly expressed like CCL4, CXCR5, CCL18, CXCL2, and so forth." (PMID 39135683, 2024).
ccRcc (1 paper, 2023). "CXCL2 can attract and regulate neutrophils thereby participate in the progression of ccRcc." (PMID 37540227, 2023).
Chlamydia infection (1 paper, 2023). "Following Chlamydia infection, mast cell-deficient mice displayed attenuated CXCL2 production, with the levels of other proinflammatory mediators including CCL2, CCL5, CXCL13, and effector mediators assessed as not being significantly altered." (PMID 37138882, 2023). "In vivo, mast cell-deficient mice displayed a dampened CXCL2 chemokine response in the uterine tracts following reproductive tract Chlamydia infection as well as reduced recruitment of neutrophils, eosinophils, and B cells during the peak of acute inflammation at day 5 post-infection." (PMID 37138882, 2023).
chronic lung infection (1 paper, 2020). "Th17 lineage cytokines (IL-17A, IL-17F, and IL-22) and chemokines (CXCL1, CXCL2, CXCL5, and CXCL8) are known to control chronic lung infection caused by mycobacteria." (PMID 33520738, 2020).
Cirrhosis (1 paper, 2023). A chronic disorder of the liver in which liver tissue becomes scarred and is partially replaced by regenerative nodules and fibrotic tissue resulting in loss of liver function. "PoPH macrophage clusters also demonstrated a unique signature, with increased CXCL2 and CD163 expression, and diminished MIF expression, relative to non-PoPH cirrhosis macrophage clusters." (PMID 37558836, 2023).
coronary artery disease (1 paper, 2018). "Recent genome-wide association studies have recognized CXCL2-related loci related to coronary artery disease risk." (PMID 30574098, 2018).
coronary atherosclerosis (1 paper, 2021). Atherosclerosis of the coronary vasculature. "Meanwhile, it is also shown that CXCL2 is significantly highly expressed in the plaques and peripheral blood mononuclear cells of patients with coronary atherosclerosis, and it might be closely related to the prognosis." (PMID 34262953, 2021).
Crush Syndrome (1 paper, 2022). Severe systemic manifestation of trauma and ischemia involving soft tissues, principally skeletal muscle, due to prolonged severe crushing. "The expression levels of inflammatory cytokines and chemokines (e.g., TNFα, IL-6, CXCL1, CXCL2, CXCR2, CCL2) in crush syndrome were significantly suppressed in TPEN-treated group." (PMID 36114355, 2022).
cutaneous leishmaniasis (1 paper, 2021). Leishmaniasis affecting the skin. "RANTES/CCL5, together with KC/CXCL1 and MIP-2/CXCL2 participate in neutrophil, monocyte, and lymphocyte recruitment to inflammatory focus and interfere in the persistence of cutaneous leishmaniasis lesions." (PMID 34178725, 2021).
diabetic retinopathy (1 paper, 2018). "While virtually nothing is known regarding CXCL2 and CXCL3 in diabetic retinopathy, CXCL8 (also called IL-8) has consistently been found to be elevated in the vitreous of diabetic retinopathy patients." (PMID 29626212, 2018).